CASR (calcium sensing receptor)
Diseases named in the same sentence as CASR in open-access papers (continued):
Sharing a sentence is not in itself a finding about the gene and the disease.
Calcium nephrolithiasis (11 papers, 2011 to 2022). The presence of calcium-containing calculi (stones) in the kidneys. "Approximately 200 nonsynonymous single-nucleotide polymorphisms have been found in the human CaSR gene, and some of these are associated with idiopathic calcium kidney stones." (PMID 33808324, 2021). "For example, several genetic variations of the calcium-sensing receptor (CASR) gene were reported to be associated with an increase in recurrent calcium kidney-stone formation." (PMID 26089600, 2015). "The relevance of CaSR in calcium homeostasis and our preliminary findings about stone former genotyping led us to study more in depth the possible role of CaSR gene polymorphisms in calcium kidney stones formation." (PMID 22107799, 2011). "Our studies suggest that CaSR is a candidate gene to explain individual predisposition to calcium kidney stones." (PMID 22107799, 2011). "Association analysis between CASR rs17251221 and subgroups of biochemical data in patients with calcium kidney stone." (PMID 21966463, 2011). "Our studies suggest that CaSR is one of the candidate genes explaining individual predisposition to calcium nephrolithiasis." (PMID 22107799, 2011). "Association analysis between CASR rs17251221 and clinical biochemical data in patients with calcium kidney stone." (PMID 21966463, 2011). "Moreover, single nucleotides CaSR polymorphisms have been associated to calcium nephrolithiasis, in particular the rs6776158 (A > G) polymorphism, resident on CaSR first promoter, which is associated with decreased transcriptional activity." (PMID 36467702, 2022). "Although further investigation is required, we assumed that the polymorphism of WDR72, DGKH, and CLDN14 could increase the risk of calcium nephrolithiasis by influencing the CaSR signaling." (PMID 35910217, 2022). "The aim of the present study was to investigate whether the CASR polymorphism (rs17251221) is associated with the development of calcium nephrolithiasis." (PMID 21966463, 2011). "Since polymorphisms of WDR72, DGKH, and CLDN14 are predicted to influence in CaSR signaling, our results emphasized the role of abnormal calcium homeostasis in calcium nephrolithiasis." (PMID 35910217, 2022). "Our studies suggest that CaSR and CLDN14 are candidate genes to explain the individual predisposition to calcium kidney stones." (PMID 26107257, 2015). "Genetic polymorphisms of CLDN14, CASR, OPN, ORAI1, and VDR were reported to be involved in calcium nephrolithiasis in humans." (PMID 24800221, 2014). "In conclusion, our results provide evidence supporting the genetic effects of CASR on the pathogenesis of calcium nephrolithiasis." (PMID 21966463, 2011). "In this study, we collected DNA samples from 480 Taiwanese subjects (189 calcium nephrolithiasis patients and 291 controls) for genotyping the CASR gene." (PMID 21966463, 2011). "Decreased activity of CaSR gene expression prompts calcium nephrolithiasis formation." (PMID 33808324, 2021). "Interestingly, the protective role of the CaSR in calcium nephrolithiasis is akin to its role in vascular calcification." (PMID 33808324, 2021).
coronary artery disease (11 papers, 2010 to 2024). "Studies have calculated an increase in the odds ratio of coronary heart disease and cardiovascular mortality when CaSR genetically varies due to single nucleotide polymorphisms and causes an increase in the circulating serum calcium." (PMID 33804544, 2021). "Polymorphisms in genes associated with the regulation of calcium levels (CASR, CYP24A1, CARS, DGKD, DGKH/KIAA0564 and GATA3) and metalloproteinases (MMP-3 and MMP-9) were also associated with an increased risk of coronary artery disease and AMI." (PMID 38478535, 2024). "Serine at position 986 of CASR may be an independent genetic predictor of angiographic coronary artery disease." (PMID 28629174, 2017).
parathyroid cancer (11 papers, 2014 to 2026). "In some malignant cancers, such as breast, prostate, and parathyroid cancers, abnormal expression of CaSR is associated with highly aggressive and metastatic tumor cells." (PMID 41522513, 2026). "The postulated primary mechanism of action in the treatment of parathyroid cancer suggests a possible interaction between cinacalcet and CaSR in the bone and/or kidneys." (PMID 40531748, 2025). "Patients with familial PHPT or parathyroid cancer had germline mutation in MEN1, CASR, and CDC73, classified as pathogenic or likely pathogenic variants." (PMID 35586626, 2022). "Several germline mutations in CDC73, MEN1, CASR, and PTH are associated with benign sporadic PHPT or parathyroid cancer." (PMID 35586626, 2022). "In parathyroid cancer, CaSR expression reduces Ki67 antigen level and therefore is inversely correlated with cell proliferation." (PMID 24576174, 2014). "Indeed, diminished calcium-sensing receptor expression has been reported in parathyroid carcinoma but is rare in benign tumours." (PMID 35805976, 2022). "Aberrant immunophenotype is characterised by a set of markers that are lost (parafibromin), down-regulated (e.g., APC protein, p27 protein, calcium-sensing receptor) or up-regulated (e.g., proliferation activity by Ki-67 exceeding 5%) in parathyroid carcinoma compared to benign parathyroid disease." (PMID 35805976, 2022). "In contrast, no mutation of the CASR gene has been demonstrated in these parathyroid carcinomas." (PMID 28122587, 2017). "Calcimimetics are orally active agonists of the CaSR, used for treating PTH hypersecretion in end stage kidney disease and parathyroid carcinoma by enhancing receptor sensitivity to extracellular calcium and inhibiting PTH secretion." (PMID 25695075, 2015). "Finally, significant negative feedback from the protein coded by the CASR gene has ben reported in a considerable proportion of parathyroid carcinoma cases having a high proliferation index." (PMID 28122587, 2017).
Alzheimer disease (10 papers, 2016 to 2025). A progressive, neurodegenerative disease characterized by loss of function and death of nerve cells in several areas of the brain leading to loss of cognitive function such as memory and language. "Soluble β-amyloid peptide (Aβ) is one of the orthosteric modulators of CaSR, while, the role and underlying mechanism of CaSR in cognitive decline in Alzheimer’s disease (AD) is unclear." (PMID 32670047, 2020). "A further contribution to the field was given by a study aimed at investigating the association of CaSR variations in Alzheimer’s disease susceptibility." (PMID 31336912, 2019). "Over time, there is evidence that CaSR plays a significant role in a variety of psychiatric diseases, including Alzheimer’s disease and depression." (PMID 40469980, 2025). "The effects of calcilytics on the release of amyloid β peptides in cells treated with amyloid β surrogates have suggested the involvement of CaSR in Alzheimer’s Disease (AD)." (PMID 31717830, 2019). "There is an emerging evidence of CaSR involvement in neurodegenerative disorders and Alzheimer's disease (AD) in particular, where the over-production of β-amyloid peptides was reported to activate CaSR." (PMID 28261055, 2017). "Future studies and clinical trials will test the validity of this Aβs•CaSR signalling-based hypothesis and the entailed therapeutic remedies for hitherto unforgiving Alzheimer’s disease." (PMID 33261147, 2020). "Altogether these findings reveal the importance and the impact which altered expression of CaSR has on maintaining the normal brain function, supporting the idea that its changes could contribute to the development and progression of pathologies such as Alzheimer's disease and stroke." (PMID 28261055, 2017).
asthma (10 papers, 2016 to 2025). "For example, the expression of calcium-sensing receptor (CaSR) is significantly increased in asthma patients, and its antagonist NPS2143 can alleviate asthma symptoms by reducing airway hyperresponsiveness (AHR) and inflammation." (PMID 40469921, 2025). "Pharmacological inhibition of the CaSR has recently been proposed as a new and effective therapeutic strategy for the treatment of asthma, given the putative pro-inflammatory role that the CaSR seems to play in the lungs." (PMID 36467702, 2022). "For example, in the lung, the CaSR has pro-inflammatory effects and thus offers a therapeutic potential for CaSR antagonists to treat asthma." (PMID 31888253, 2019). "CaSR has recentlyalso been implicated in noncalcitropic pathophysiologies like asthma,gut inflammation, and cancer." (PMID 38751613, 2024). "While some reports suggest an anti-inflammatory effect of spermine in the lungs, spermine and other polyamines were shown to promote increased pulmonary fibrosis, airway hyperresponsiveness and asthma severity by activating the CaSR expressed in airway smooth muscle cells and epithelial cells." (PMID 37153788, 2023). "Furthermore, a study focusing on asthma showed that asthmatic patients and allergen-sensitized mice have higher expression levels of CaSR, linking abnormal CaSR expression to yet another inflammatory disease." (PMID 31191301, 2019). "Recently it has also been suggested that calcilytics could be repurposed for treating asthma, as upregulated CaSR-signalling has been shown to mediate increased airway hyperresponsiveness in an asthmatic mouse model and in human lung tissue isolated from asthmatic patients." (PMID 27725162, 2016).
gastric cancer (10 papers, 2019 to 2025). A primary or metastatic malignant neoplasm involving the stomach. "Excessive calcium ions enhance the growth and metastasis of gastric cancer through pathways such as calcium-sensing receptor (CaSR) and the AKT/β-catenin pathway." (PMID 38370477, 2024). "CaSR has been reported to adjust cell proliferation through the Wnt/β-catenin pathway in gastric cancer and colonic epithelium." (PMID 32671062, 2020). "CaSR expression was enhanced in gastric cancer specimens and positively correlated with serum calcium concentrations, tumor progression and poor survival." (PMID 33113952, 2020). "On the contrary, in gastric cancer, CaSR activation enhanced Wnt/β-catenin signaling in tumor cells, and consequently promoted cell proliferation, migration, and invasion." (PMID 32671062, 2020). "A recent report on the CaSR promoting gastric cancer progression mentions a few experiments where they used calcilytics in vivo to bring down tumor growth and metastasis." (PMID 32117726, 2020). "The team went on to show that there is a functional link between CaSR and human telomerase reverse transcriptase (hTERT) in gastric cancers, where calcilytics inhibited Ca-mediated upregulation of hTERT and accumulation of p-Akt." (PMID 32117726, 2020). "Akt was reported to be an immediate responder to CaSR activation in gastric cancer cells." (PMID 36348350, 2022). "An oncogenic role of CasR has been described in breast, renal, prostate and gastric cancers." (PMID 33113952, 2020). "In addition, the same group has stablished a functional linkage between CasR and the oncogene telomerase reverse transcriptase in the development of gastric cancers." (PMID 33113952, 2020). "A protumoral effect of CasR has also been reported in gastric cancer." (PMID 33113952, 2020). "CaSR also influences AKT expression in various contexts, including osteosarcoma cell proliferation, human telomerase reverse transcriptase in gastric cancer, and neurite outgrowth in developing chicken embryos." (PMID 40059879, 2025). "Studies have also shown that calcium-sensing receptor (CaSR) and TRPV4 were colocalized in gastric cancer cells, and CaSR activation evoked TRPV4-mediated Ca2+ entry promote gastric cancer cells proliferation." (PMID 31235786, 2019).
Hypomagnesemia (10 papers, 2017 to 2025). An abnormally decreased magnesium concentration in the blood. "Aminoglycosides are thought to cause hypomagnesemia by activating the calcium-sensing receptor (CaSR) in the thick ascending limb (TAL) of the loop of Henle and in the distal convoluted tubule (DCT)." (PMID 40868117, 2025). "Hypomagnesemia inhibits the Wnt/β-catenin signaling pathway and activates the calcium-sensing receptor in VSMCs." (PMID 37233174, 2023). "Whilst low levels of magnesium are known to stimulate PTH secretion by activation of the calcium-sensing receptor, only severe hypomagnesemia with serum magnesium < 0.5 mmol/l and an intracellular magnesium deficit is supposed to induce a paradoxical block of PTH secretion." (PMID 36190530, 2022).
nephrocalcinosis (10 papers, 2015 to 2025). Nephrocalcinosis is a disorder that occurs when too much calcium is deposited in the kidneys. "Only one paper has reported the onset of nephrocalcinosis after 6 months of cinacalcet therapy in a patient with heterozygous CASR mutation." (PMID 36090548, 2022). "CLDN14 expression would be increased by the activating mutation of CaSR gene and causing nephrocalcinosis." (PMID 26107257, 2015). "Infants with NSHPT should have low urinary calcium excretion because of their underlying defect in the CaSR, and thereby should not be at high risk for developing nephrocalcinosis during calcitriol and calcium replacement following parathyroidectomy." (PMID 39129820, 2024).
renal cell carcinoma (10 papers, 2014 to 2025). "In addition, Brenner lab showed that the bone metastasis caused by renal cell carcinoma (RCC) was promoted by the extracellular Ca2+ through the CaSR." (PMID 32117726, 2020). "Calcium, via overexpressed CaSR, promotes the migration and proliferation of bone-metastasizing renal cell carcinoma (RCC) cells by activating downstream pathways." (PMID 40860192, 2025). "Frees and colleagues demonstrated that calcium-stimulated CasR increased cell migration and proliferation in human 768-O renal cell carcinoma cells and, in a xenograft mouse model in vivo, the injection of cells overexpressing CasR increased bone metastasis." (PMID 33113952, 2020). "We recently demonstrated that the expression of CaSR was highest in specimens and primary cells of patients with renal cell carcinoma who developed bone metastases in a period of five years after surgery." (PMID 29644008, 2018). "Calcium-sensing receptor (CaSR) was activated by extracellular Ca2+, which promoted bone metastasis in renal cell carcinomas." (PMID 30326911, 2018). "The implication of CasR in bone metastasis was also observed in renal cell carcinoma." (PMID 33113952, 2020). "For example, in renal cell cancer, in addition to AKT signaling pathway, PLCγ-1, p38α, JNK, and PTEN, but not ERK1/2, were involved in CaSR-dependent bone metastasis and cellular proliferation." (PMID 32671062, 2020).
colitis (9 papers, 2019 to 2024). Inflammation of the colon. "Intestine-specific knockout of the CaSR renders mice more susceptible to dextran sulphate sodium (DSS)-induced colitis." (PMID 31888253, 2019). "In this study, we have shown that CaSR inhibition in medium-grade colitis consistently and significantly reduced several signs and symptoms, including colon shortening, of acute inflammation." (PMID 39770982, 2024). "The fact that inhibition of the CaSR seems to provide a greater benefit in a setting of more severe colitis is especially interesting, as this suggests a truly disease-specific effect, which would be a further boon for a therapeutic use of these drugs." (PMID 39770982, 2024). "In our previous study, we used a model of rather severe colitis with 3.5% DSS to investigate pharmacological targeting of the CaSR in colitis as a preventative/therapeutic measure against this disease." (PMID 39770982, 2024). "Our results also suggest that the allosteric modulators of the CaSR differentially influence key parameters in the DSS-induced colitis mouse model." (PMID 31888253, 2019). "Our study is the first to use oral administration of CaSR allosteric modulators in pre-clinical colitis models." (PMID 31888253, 2019). "This confirms that a high protein diet, while potentially modulating the CaSR, has a deleterious effect on colitis on its own." (PMID 31888253, 2019). "Their study found that mice lacking CaSR specifically in their intestinal epithelial cells were significantly more susceptible to dextran sulphate sodium (DSS)-induced colitis." (PMID 38994933, 2024). "Additionally, mice with the CaSR knockout were more susceptible to DSS-induced inflammation, leading to colitis." (PMID 39770982, 2024). "We showed that the calcilytic NPS 2143 reduced the clinical symptom score of mice with DSS-induced colitis, suggesting that CaSR inhibition may be a new therapeutic approach for the treatment of IBD to alleviate colitis symptoms." (PMID 39770982, 2024). "Other studies also suggest that Trp plays a role in the recovery of colitis and in the function of intestinal homeostasis by caspase recruitment domain family member 9 (Card9), calcium-sensing receptor (CaSR), and aryl hydrocarbon receptor (AHR) ligands in the intestine." (PMID 35747264, 2022). "Taken all the parameters into consideration, our data suggests that inhibiting the CaSR with orally administered calcilytics may alleviate colitis symptoms." (PMID 31888253, 2019). "It is suggested that activation of the CaSR in the intestines attenuates DSS-induced colitis." (PMID 31888253, 2019). "To test our hypothesis that the CaSR reduces intestinal inflammation, we assessed the effects of nutritional and pharmacological agonists of the CaSR in a colitis model." (PMID 31888253, 2019). "Thus, in this follow-up study, we tested whether inhibition of the CaSR with NPS 2143 would be more protective in a medium-grade colitis induced with 2.5% DSS." (PMID 39770982, 2024). "Therefore, in the present follow-up study we aimed to test the hypothesis of whether pharmacological inhibition of the CaSR would have a stronger effect in a medium-grade colitis induced by a 2.5% DSS treatment." (PMID 39770982, 2024). "Moreover, cinacalcet, a positive allosteric modulator of the CaSR, worsened the colitis symptoms." (PMID 39770982, 2024). "However, it was unclear whether the potential of CaSR inhibition to reduce colitis may have been overshadowed by the severity of the induced inflammation in our previous study." (PMID 39770982, 2024). "However, the mechanism through which CaSR activates NLRP3 in colitis needs further study." (PMID 34880751, 2021). "Previously, we showed that inhibition of the CaSR with NPS 2143 ameliorates the clinical symptoms of mice with acute, chemically induced (3.5% DSS) severe colitis compared with vehicle-treated mice." (PMID 39770982, 2024). "Therefore, we tested if CaSR inhibition could prevent medium-grade colitis." (PMID 39770982, 2024).